LMO2 (LIM domain only 2)
Diseases named in the same sentence as LMO2 in open-access papers (continued):
Sharing a sentence is not in itself a finding about the gene and the disease.
Wilms tumor (4 papers, 2020 to 2024). An embryonal neoplasm characterized by the presence of epithelial, mesenchymal, and blastema components. "We found LMO1 rs2168101 G > T and rs11603024 C > T as well as LMO2 rs7933499 G > A were significantly associated with Wilms tumor risk." (PMID 38937681, 2024). "Referring to the LMO2 gene, only the rs7933499 G > A was significantly associated with an enhanced risk of developing Wilms tumor." (PMID 38937681, 2024). "This deletion disrupted the LMO2 gene and was associated with a significant increase in the risk for Wilms tumor development." (PMID 38069245, 2023). "In brief, the current epidemiological genetic association study identified that several functional SNPs in the LMO family genes, namely, rs2168101 G > T and rs11603024 C > T in the LMO1 gene and rs7933499 G > A in the LMO2 gene, are significantly associated with susceptibility to Wilms tumor." (PMID 38937681, 2024). "The results indicated that LMO1 and LMO2 genetic variants were associated with Wilms tumor susceptibility, which may help identify additional genetic susceptibility loci as novel biomarkers for the diagnosis and treatment of Wilms tumor." (PMID 38937681, 2024). "Most patients with so-called WARG deletions develop Wilms tumor only in cases when the LMO2 gene is affected by deletion." (PMID 38069245, 2023). "The increased risk for Wilms tumor in patients with WAGR syndrome is caused by a haploinsufficiency of WT1 (OMIM: 607102); it has been suggested that LMO2 gene haploinsufficiency contributes to a further increase in this risk, based on a genotype–phenotype correlation analysis." (PMID 36011342, 2022). "Additionally, given the structural similarity of the LMO gene family, we reasonably speculated that LMO2 and LMO4 gene polymorphisms might be correlated to Wilms tumor susceptibility as LMO1 gene did." (PMID 38937681, 2024). "In our cohort, there were four patients affected by Wilms tumor with LMO2 deletion, one patient with LMO2 deletion and no Wilms tumor until she was 3 years old, and one patient without LMO2 deletion and Wilms tumor until he was 11 years old." (PMID 36011342, 2022). "The first upstream deletion in the patient does not affect the LMO2 gene, so we could hypothesize his chances of developing a Wilms tumor with only that deletion were low." (PMID 38069245, 2023).
anemia (3 papers, 2009 to 2023). A reduction in the number of red blood cells, the amount of hemoglobin, and/or the volume of packed red blood cells. "The transcription factors Tal1, Gata1, Lmo2 and Fog1 (Zfpm1) all had lower expression in C57BL/6 than BALB/c consistent with more severe anaemia in C57BL/6." (PMID 19365556, 2009). "LMO2 null mice die around E9 of severe anemia, witha lack of any YS hematopoiesis." (PMID 24324557, 2013).
colorectal cancer (3 papers, 2016 to 2025). A primary or metastatic malignant neoplasm that affects the colon or rectum. "The function of LMO2 to regulate cell proliferation has been found involved during tumourigenesis, and the inhibition of LMO2 showed apoptosis induction in breast and colorectal cancer." (PMID 41385269, 2025). "However, in the current study, the specific cytosolic localization of LMO2 was observed in both breast and colorectal cancer cells." (PMID 27779255, 2016). "Also, anti-LMO2 and anti-DVL1-1/2 immunofluorescence staining in breast and colorectal cancer cells revealed that LMO2 was predominantly located and co-localized with DVL-1/2 in the cytoplasm." (PMID 27779255, 2016).
lung carcinoma (3 papers, 2021 to 2023). "The expression levels of GATA1 and LMO2 were low and associated with advanced lymph node metastasis and staging in lung cancer (left two panels)." (PMID 35743687, 2022). "However, only GATA1 and LMO2 showed more than a two-fold change between normal parts and tumor parts in lung cancer." (PMID 35743687, 2022). "Two of the most frequently dysregulated transcription factors are co-expressed in lung cancer and PAH (FOXM1 and FOXF1), while the other six frequently deregulated transcription factors are co-expressed only in lung cancer (TCF21, SOX17, TAL1, LMO2, KLF2, and TBX4)." (PMID 36661515, 2023). "When cross-analyzing ADAMTS8 based on the levels of GATA1 in survival time, lung cancer patients with low-level ADAMTS8 survived for a shorter period when compared with high-level based on low GATA1 but not LMO2 expression." (PMID 35743687, 2022). "Moreover, FOXF1 is also co-expressed in the CCP of the LC RNA-Seq datasets, along with seven of the most frequently dysregulated TFs (FOXM1, SOX17, TAL1, TCF21, TBX4, LMO2, and KLF2), suggesting its importance as a regulator of gene expression during lung cancer progression." (PMID 36661515, 2023).
severe combined immunodeficiency (3 papers, 2004 to 2018). Severe combined immunodeficiency (SCID) comprises a group of rare monogenic primary immunodeficiency disorders characterized by a lack of functional peripheral T lymphocytes resulting in early-onset severe respiratory infections and failure to thrive. "The adverse events arising during X-linked severe combined immunodeficiency gene therapy involved integration of an MLV vector near the transcription start region of the LMO2 proto-oncogene." (PMID 15314653, 2004).
viral infection (3 papers, 2022 to 2024). "Three relevant transcription factors, namely, SP1 (TTRUST database; also identified in the IPA analysis), which has been described as involved in viral transcription, LMO2, a regulator of T-cell translocation, and AP1, are related to viral infection and ROS (Transcription Factor Targets database)." (PMID 38778280, 2024).
asthma (2 papers, 2019 to 2020). "Prediction of asthma by cutting off CG site methylation levels of LMO2, GSTM1, and IL10 according to the ROC curve followed by DeLong test." (PMID 31214241, 2019). "Prenatal paternal smoking led to epigenetic modifications in certain genes as such as LIM Domain Only 2 (LMO2) and interleukin-10 (IL-10) via cytosine-phosphate-guanine (CpG) methylation, and these modifications are correlated to childhood asthma development." (PMID 32867076, 2020).
B cell lymphoma (2 papers, 2015 to 2023). "To date, a number of biomarkers with a diagnostic value for each B-cell lymphoma subtype have been determined: BCL2, BCL6, CD10, CD21, and STMN1 in FL; D1 and SOX11 in MCL; FOXP1 and MUM1 in ABC-DLBCL; CD10, BCL2, BCL6, LMO2, and GCET1 in GC-DLBCL; and CD30, CD15, EBV, BOB1, OCT2, and CD79a in HL." (PMID 37894763, 2023).
colon cancer (2 papers, 2016 to 2021). "As shown in the interaction network, immune-related gene PLCG2 and IGF1, which are up-regulated in colon tumor samples, have significantly strong correlation with several TFs: FOXP3, IKZF1, CBX7, LMO2, MEF2C, EPAS1 and MAF." (PMID 33996273, 2021).
eosinophilia (2 papers, 2021 to 2023). "Out of 11 cases of T-LBLs linked to myeloid/lymphoid neoplasms with eosinophilia, a study found that nine of them did not have LMO2, indicating a distinct molecular process for T-LBLs associated with myeloid/lymphoid neoplasms with eosinophilia." (PMID 38179383, 2023). "In our study, we would suggest that LMO2 immunostaining, as part of the diagnostic panel for T-LBL, may represent a useful marker to identify T-LBL developing in the context of myeloid/lymphoid neoplasms with eosinophilia." (PMID 34205834, 2021).
glioblastoma (2 papers, 2016 to 2020). The most malignant astrocytic tumor (WHO grade IV). "In the current study, analysis of the TCGA Pan-cancer dataset revealed that LMO2 expression was elevated in glioblastoma but reduced in most other cancer types, particularly in epithelial-derived tumors such as breast, colon, rectal, lung, and kidney cancer." (PMID 27779255, 2016).
glioma (2 papers, 2016 to 2022). A benign or malignant brain and spinal cord tumor that arises from glial cells (astrocytes, oligodendrocytes, ependymal cells). "A recent study demonstrated that an oncogenic transcription factor Lim domain only 2 (LMO2) increases glioma stem cells by inducing JAG1 expression." (PMID 27029061, 2016). "Therefore, the aim of this study was to investigate the oncogenic role of cytoplasmic LMO2 in glioma stem cells (GSCs) and to elucidate the signaling mechanisms induced through complex with proteins that bind to cytoplasmic LMO2." (PMID 35805116, 2022). "Here, we identified LMO2 as a cytoplasmic activator for signal transducer and activator of transcription 3 (STAT3) signaling in glioma stem cells (GSCs) through biochemical and bioinformatics analyses." (PMID 35805116, 2022). "In the clinical data, the LMO2 expression level and pY705-STAT3 reverse-phase protein array score were positively correlated in the TCGA GBMLGG (Low-grade glioma) dataset." (PMID 35805116, 2022).
neuroblastoma (2 papers, 2016 to 2023). Neuroblastoma (NB) is the most common solid, extracranial childhood tumor. "LMO1, LMO2, and LMO3 are functionally redundant T-ALL oncogenes, so, we reasoned that loss of lmo1 expression in zebrafish might stimulate the upregulation of other lmo family members during neuroblastoma pathogenesis." (PMID 37183825, 2023).
osteosarcoma (2 papers, 2017 to 2022). A usually aggressive malignant bone-forming mesenchymal neoplasm, predominantly affecting adolescents and young adults. "In contrast, the expressions of LMO2, MAML3, and SIRT1 were downregulated in all osteosarcoma cell lines." (PMID 35734428, 2022).
X-linked SCID (2 papers, 2010 to 2012). "In addition, patients undergoing gene therapy for X-linked severe combined immunodeficiency developed clonal T-cell proliferation as a result of aberrant transcriptional activation of Lmo2 when the gene therapy vector integrated near Lmo2." (PMID 23285212, 2012).
B-cell neoplasm (1 paper, 2021). A group of heterogeneous lymphoid tumors generally expressing one or more B-cell antigens or representing malignant transformations of B-lymphocytes. "Like other mature B cell neoplasms, FL expresses pan-B cell antigens (CD19, CD22, CD79a and PAX5), and is also by definition positive for germinal center markers, such as BCL6, HGAL and LMO2." (PMID 34898578, 2021).
bladder cancer (1 paper, 2024). "The top 50 differentially expressed genes of germinal center-related B-cell subtypes were put into the TCGA database for comparison, and the expression of LMO2, AICDA and NEIL1 in bladder cancer was observed." (PMID 38216927, 2024).
cardiomegaly (1 paper, 2022). "Further analysis did, however, reveal that LMO2 intron variants were significantly associated with “Cause of death: cardiomegaly” (p = 3.0−9) and “Cause of death: dilated cardiomyopathy” (p = 1.3−8)." (PMID 35548346, 2022).
coloboma (1 paper, 2018). An abnormality in which a part of a structure in one or both eyes is missing. "The close coordination between the development of both structures is highlighted by the ability of the dilated hyaloid vein in zebrafish lmo2 mutants to disrupt fissure closure and cause inferior coloboma." (PMID 29522511, 2018).
heart failure (1 paper, 2022). Inability of the heart to pump blood at an adequate rate to meet tissue metabolic requirements. "Here we used whole-exome sequencing and bioinformatics on human patient data to identify 3 genes (API5, HSPB7, and LMO2) suggestively associated with heart failure that were also predicted to play a broader role in disease aetiology." (PMID 35548346, 2022). "We identified a subset of three genes (API5, HSPB7, and LMO2) predicted to play a broader role in heart failure aetiology, and undertook in vivo phenotypic assessment in zebrafish." (PMID 35548346, 2022).
Immunodeficiency (1 paper, 2018). Failure of the immune system to protect the body adequately from infection, due to the absence or insufficiency of some component process or substance. "A pertinent example of this phenomenon in humans can be found in the development of T-ALL in severe combined immunodeficiency patients who received retrovirally transduced, gene-corrected autologous hematopoietic stem cells, where the viral LTR integrated into the vicinity of the LMO2 gene." (PMID 29941549, 2018).
liver cancer (1 paper, 2017). An epithelial or non-epithelial malignant neoplasm that arises from the liver. "One IS was found within the genotoxicity-associated LMO2 gene in 5002 but was absent at later time points, and no further integration hotspots or single events were located within genes previously associated with AAV-driven liver cancer development." (PMID 28462816, 2017).
Myelodysplasia (1 paper, 2024). Clonal hematopoietic stem cell disorders characterized by dysplasia (ineffective production) in one or more hematopoietic cell lineages, leading to anemia and cytopenia. "The oncogenic events occurred from 1.3 to 14.8 years after GT and were associated predominantly with insertional activation of the proto-oncogenes LIM domain only 2 (LMO2) for T-cell acute lymphoid leukemia or MECOM for myelodysplasia/myeloid leukemia." (PMID 38688902, 2024).
sarcoma (1 paper, 2022). A usually aggressive malignant neoplasm of the soft tissue or bone. "In order to reveal the association between the expressions of five TcoF-related genes (LMO2, MAML3, MTF2, RBPMS, and SIRT1) in the risk model and immune cell infiltration, the data on sarcoma from the TIMER database were collected." (PMID 35734428, 2022). "Mutations of each gene (LMO2, MAML3, MTF2, RBPMS, and SIRT1) in sarcoma were 6, 7, 6, 3, and 5%, respectively, with the most common changes in the mRNA expression." (PMID 35734428, 2022).
cancer (41 papers, 2008 to 2026). A tumor composed of atypical neoplastic, often pleomorphic cells that invade other tissues. "Indeed, although some gene therapy patients have developed cancer following insertion of the therapeutic construct into or very close to LMO2 gene, another case was associated with an insertion 35 kbps upstream of (and in an opposite orientation to) the same proto-oncogene." (PMID 21246045, 2011). "Altogether, we show that LMO2 plays a role in maintaining cellular plasticity in MECs, adding insight into the normal differentiation programs hijacked by cancer cells to drive tumor progression." (PMID 40709263, 2025). "In the case of cancers, aberrant expression of LMO2 induces tumor aggressiveness and CSC characteristics in T-ALL and GBM." (PMID 35805116, 2022). "Among these genes, PICALM (targeted by EP300), DDX6 (targeted by YY1) and LYL1 (targeted by LMO2) are reported on the COSMIC cancer gene list." (PMID 32850701, 2020). "CTCF, EP300 and LMO2 are listed in the Catalog Of Somatic Mutations In Cancer (COSMIC) as genes that are causally implicated in cancer if mutated." (PMID 32850701, 2020). "Since it functions as a tumor suppressor in epithelial cells, it is possible that the downregulation of LMO2 occurs during the early stages of tumorigenesis in many cancers." (PMID 27779255, 2016). "Meanwhile, our analysis of the cancer genome atlas (TCGA) online pan-cancer dataset revealed that LMO2 expression was declined in several kinds of solid tumors, particularly in breast and colorectal carcinoma." (PMID 27779255, 2016). "Studies conducted on human cancers by other groups from have indicated that LMO2, a transcription factor expressed in blood and vasculature acts as a transcriptional suppressor of miR-142." (PMID 23285103, 2012). "We observed similar cancer-specific H3K4me3-BDs associated with hijacking of super-enhancers of other common oncogenes in B cell (MAF, MYC, and FGFR3/NSD2) and T cell malignancies (LMO2, TLX3, and TAL1)." (PMID 34933939, 2022). "Pathways derived from NOTCH3, PARD3, CACNA1A, MAX, RAD50, FUS and LMO2 were cancer-related." (PMID 34540367, 2021). "Notably, recent studies revealed that LMO2 was expressed in a variety of normal tissues and cancer cells, with either nuclear or cytoplasmic location." (PMID 27880729, 2017). "Further investigations into this may help provide novel strategies for cancer therapy by targeting LMO2 and the Wnt signaling pathway in the future." (PMID 27779255, 2016). "The discovery of LMO2 in some B cell neoplasias and in some epithelial cancers suggests a more ubiquitous function as an oncogenic protein, and that the current development of novel inhibitors will be of great value in future cancer treatment." (PMID 26108219, 2015). "Our analysis of the LMO2 +1 enhancer now shows that leukaemic cells can exploit regulatory hierarchies resurrected from normal embryonic development, and therefore provides molecular evidence for parallels between early embryonic cells and cancer." (PMID 23708655, 2013). "In addition, members containing these domains have significantly abundant functions in cancer, speculating that the main functions of LMO2 are involved in carcinogenesis." (PMID 37573405, 2023). "Thus, Cy induced down regulation in Ras, LMO2, MCM4 and MCM7 genes might shed light on the mechanisms underlying the anti-cancer effects of Cy." (PMID 24466173, 2014). "In addition, established cancer genes like Lmo2, RhoH, Trim33, Mll, and Hspca are candidate target genes of less frequently mutated CISs, indicating that lower ranked CISs (carrying 4–5 insertions) may represent bona fide cancer genes." (PMID 18485879, 2008). "In the hub interaction score 23 and the highest number of interactions, the topmost hub node was LMO2 (LIM Domain Only 2) key regulator of hematopoietic stem cells and cancer malignancies." (PMID 36644780, 2023).